CSNK1G3 (casein kinase 1 gamma 3)
Description:
Serine/threonine-protein kinase. Casein kinases are operationally defined by their preferential utilization of acidic proteins such as caseins as substrates. It can phosphorylate a large number of proteins. Participates in Wnt signaling. Regulates fast synaptic transmission mediated by glutamate (By similarity).
Synonyms: CKI-gamma 3; CSNK1G3L
Tractability: Small molecule: a structure with a bound ligand is known; a high-quality ligand is known; it has a high-quality binding pocket; it belongs to a druggable protein family. Antibody: its Gene Ontology location is reachable by antibodies, with medium confidence. PROTAC: ubiquitination databases record sites on it; its protein half-life has been measured; a small molecule that binds it is known.
Target class: Enzyme; CK1 protein kinase group; Kinase; CK1 protein kinase CK1 family; CK1 protein kinase CK1-g; Protein Kinase
Gene: Protein-coding gene on chromosome 5 (123,512,067 to 123,617,049, forward strand). Ensembl gene ENSG00000151292.
Subcellular location: Cytoplasm
Gene Ontology:
Molecular function: protein binding; protein serine/threonine kinase activity; protein kinase activity; ATP binding; protein serine kinase activity
Biological process: endocytosis; positive regulation of canonical Wnt signaling pathway; protein modification process; signal transduction
Cellular component: plasma membrane; cytoplasm
Genetic constraint (gnomAD): Loss-of-function variants: 9 observed, 25.52 expected, observed/expected ratio (o/e) 0.35, 90% interval 0.21 to 0.62. The upper end of that interval is the gene's LOEUF score, 0.62, which puts it in group 2 of 6, group 1 being the genes least tolerant of losing a copy. Missense variants: 184 observed, 283.61 expected, observed/expected ratio (o/e) 0.65, 90% interval 0.57 to 0.73. Synonymous variants: 92 observed, 97.23 expected, observed/expected ratio (o/e) 0.95, 90% interval 0.8 to 1.12.
Homologues: Orthologues: chimpanzee CSNK1G3 (99% identical), macaque CSNK1G3 (99% identical), pig CSNK1G3 (99% identical), rat Csnk1g3 (99% identical), rabbit CSNK1G3 (98% identical), mouse Csnk1g3 (97% identical), guinea pig CSNK1G3 (97% identical), tropical clawed frog csnk1g3 (96% identical), dog CSNK1G3 (74% identical), Caenorhabditis elegans csnk-1 (60% identical), Drosophila melanogaster CG9962 (25% identical). Paralogues in human: CSNK1G2 (76% identical), CSNK1G1 (75% identical), CSNK1D (44% identical), CSNK1E (44% identical), CSNK1A1 (38% identical), CSNK1A1L (36% identical), TTBK1 (30% identical), TTBK2 (29% identical), VRK1 (23% identical), VRK2 (21% identical), CDC7 (18% identical), VRK3 (16% identical).
Diseases named in the same sentence as CSNK1G3 in open-access papers:
CSNK1G3 is named in the same sentence as 13 diseases in open-access papers, as found by Europe PMC text mining. Sharing a sentence is not in itself a finding about the gene and the disease. The quoted sentences say what the papers report.
COVID-19 (1 paper, 2022). A disease caused by infection with severe acute respiratory syndrome coronavirus 2. "For the suggestive COVID-19 protective signal observed on chromosome 5, the promoter regions of two flanking genes CEP120 and CSNK1G3 were less accessible in the deceased group at hospital admission and follow-up." (PMID 35648852, 2022).
epilepsy (1 paper, 2025). A brain disorder characterized by episodes of abnormally increased neuronal discharge resulting in transient episodes of sensory or motor neurological dysfunction, or psychic dysfunction. "Circ_Csnk1g3 participates in necroptosis and inflammatory signaling pathways in epilepsy by regulating the encoding peptide Csnk1g3-85aa, showing significant potential as a new therapeutic target and diagnostic marker for epilepsy." (PMID 39920301, 2025). "This suggests that circRNA-Csnk1g3 has translation potential and may be involved in the pathogenesis of epilepsy by encoding polypeptide segments such as Csnk1g3- 85aa15." (PMID 39920301, 2025). "In this study, we validated that Circ_Csnk1g3 encoded a novel peptide, Csnk1g3-85aa, which was significantly increased in epileptic hippocampal tissue and an HT22 cell model of epilepsy." (PMID 39920301, 2025). "in the prevention and treatment of epilepsy, as manifested in its regulation of the Circ_Csnk1g3/Csnk1g3-85aa/ CK1γ3/TNF-α pathway to inhibit hippocampal neuronal necroptosis and inflammation." (PMID 39920301, 2025).
kidney stones (1 paper, 2025). "Furthermore, our pathway enrichment analysis demonstrated that LAMA2 and CSNK1G3 were linked to Mannose/Threonate and kidney stone formation through shared pathways, including the PI3K‐Akt signaling pathway, ECM–receptor interaction, and Focal adhesion." (PMID 40842671, 2025). "Plasma metabolites (Mannose and Threonate) are key mediators in the diet–kidney stone nexus, and the downregulation of LAMA2 and CSNK1G3 is associated with a decreased risk of kidney stones, providing insights into potential therapeutic targets." (PMID 40842671, 2025). "Moreover, our analysis indicated that LAMA2 and CSNK1G3 are key genes that are downregulated in kidney stones." (PMID 40842671, 2025).
migraine (1 paper, 2017). "After applying a Bonferroni correction, three SNPs located in ELOVL6, SARDH and CSNK1G3 pass the significance threshold suggesting a particularly important role for these genes in migraine susceptibility." (PMID 28361102, 2017). "The replication study supported significant association with the genes ELOVL6 (P = 0.00035), SARDH (P = 0.00081), and CSNK1G3 (P = 0.00037) and migraine." (PMID 28361102, 2017).
renal cell carcinoma (1 paper, 2021). "Only enhanced expression of CSNK1G3 in renal cell carcinoma has been reported." (PMID 33861751, 2021).
vitiligo (1 paper, 2021). Generalized well circumscribed patches of leukoderma that are generally distributed over symmetric body locations and is due to autoimmune destruction of melanocytes. "Expression of CSNK1G3, a gene related to human vitiligo, is significantly reduced in C57BL/6 black mice with tyrosinase-induced depigmented skin." (PMID 34220935, 2021).
tumor (3 papers, 2012 to 2022). "While the silencing of circAnkib1 and circCsnk1g3 showed a profound effect on tumor growth in vivo, the silencing of linear Ankib1 and Csnk1g3 transcripts with shRNAs specific to the linear isoforms did not impact tumor growth." (PMID 36433954, 2022). "In fact, the authors observed that when miR-181b was inhibited, the EMT-promoting effects caused by increased circ-CSNK1G3 were notably reversed, and overexpression of TIMP3 was also able to reverse tumor growth." (PMID 35813211, 2022). "Therefore, anti-circRNA therapies focused on reducing circ-CSNK1G3 levels may modulate tumor growth." (PMID 35813211, 2022).
infectious disease (1 paper, 2025). A disorder directly resulting from the presence and activity of a microbial, viral, or parasitic agent in humans. "In cattle, the CSNK1G3 gene may be a regulatory gene for some infectious diseases caused by bacterial or viral agents, which can be transmitted through semen and affect fertility." (PMID 39794685, 2025).
CSNK1G3 also shares sentences with these, for which no sentence is quoted: calculus (1 paper); cancer (1); developmental delay (1); Hypertension (1); renal carcinoma (1).